CD44 (CD44 molecule (IN blood group))
Diseases named in the same sentence as CD44 in open-access papers (continued):
Sharing a sentence is not in itself a finding about the gene and the disease.
gastric cancer (continued). "In addition, highly expressed CD44 can activate the Wnt signalling pathway and promote the occurrence and metastasis of gastric cancer." (PMID 36316684, 2022). "Moreover, AQP3 promotes the expression of CD44, a cancer stem marker, through the Wnt/β-catenin signaling pathway in gastric cancer cells." (PMID 35252273, 2022). "In gastric cancer, overexpression of p-Stat3 increased sphere formation from CD44+ CSCs." (PMID 35600882, 2022). "In addition, by reading the literature, it was found that the expression of the CD44 isoform CD44v6 in gastric cancer was related to the location of the tumour, depth of invasion, lymph node metastasis, Lauren classification and TNM stage." (PMID 36316684, 2022). "Interestingly, the results of IHC revealed that there was a spatial co-expression pattern of SPP1+ macrophages and CD44+ epithelial cells in gastric cancer specimens, providing evidence for the crosstalk between these two cell types." (PMID 36612160, 2022). "Therefore, we used The Cancer Genome Atlas (TCGA) database to analyse the relative expression level of CD44 RNA in gastric cancer and validated our findings in the Gene Expression Omnibus (GEO) database." (PMID 36316684, 2022). "Indeed, a subset of AGC patients with CD44 overexpression, a gastric cancer stem-cell biomarker, had better overall survival when treated with vismodegib in combination with cytotoxic chemotherapy." (PMID 35281856, 2022). "CD44 serves as a marker for several tumour stem cells, including gastric cancer." (PMID 36316684, 2022). "Likewise, sulfasalazine suppresses CD44-dependent tumor growth promoting p38 in gastric cancer cells." (PMID 36457557, 2022). "Previous study showed that IGF2BP3 could form a ternary complex of circFNDC3B-IGF2BP3-CD44 mRNA to increase CD44 expression in the translation process, finally promoting the migration and invasion of gastric cancer cells." (PMID 34986849, 2022). "By contrast, it has been previously demonstrated that CD44 O-glycans shortening increased hyaluronan binding capacity and may promote migratory pro-invasive cancer cell phenotypes in gastric cancer." (PMID 35547758, 2022). "Furthermore, cell proliferation and migration were reduced after the knockdown of CD44 expression in gastric cancer cells." (PMID 36316684, 2022). "Collectively, this study demonstrates that GALNT1 overexpression in gastric cancer promotes the Wnt/β-catenin signaling pathway via abnormal O-glycosylation of CD44 to enhance malignancy, providing a novel strategy for the development of therapeutic reagents against gastric cancer." (PMID 36439876, 2022). "Although it has been proposed that FGFR2 is coexpressed and colocalized with CD44 in gastric cancer cells, it is still unclear whether the association between these two proteins exists in ECs." (PMID 36463112, 2022). "Even though the binding site of CHI3L1 to CD44 is not clear, it is known that CHI3L1 can bind to CD44 and cause gastric cancer cell metastasis." (PMID 34758182, 2022). "Reduces CD44 expression levels in mice models for gastric cancer." (PMID 35785191, 2022). "In conclusion, CD44 is expected to become a new immunotherapeutic target for gastric cancer by further exploration of the specific mechanism of CD44 and various immune cells and how it affect the survival and prognosis of gastric cancer patients." (PMID 36316684, 2022). "In addition, CD44 affected the survival and prognosis of gastric cancer patients by affecting the infiltration of some immune cells." (PMID 36316684, 2022). "We used GSEA to further explore the specific molecular mechanism of CD44 in gastric cancer." (PMID 36316684, 2022). "A phase II clinical trial of patients with gastric cancer showed that patients who received chemotherapy with Vismodegib–a hedgehog inhibitor–held a survival advantage if their tumour had high expression of CSC marker CD44." (PMID 33628765, 2021). "miR-145 decreased the chemoresistance in gastric by targeting CD44 in gastric cancer." (PMID 34631898, 2021).
gastric cancer (continued). "A prospective trial that enrolled 228 patients with resectable gastric cancer found that during the long-term follow-up, among the 99 cytokeratin-positive tumors, distant metastases were observed in half of the CD44-positive patients, compared with 19% of patients in the CD44-negative group." (PMID 34068319, 2021). "In addition, SALL4 knockdown downregulates the expression of a multifunctional transmembrane glycoprotein CD44 in gastric cancer and lung adenocarcinoma cells." (PMID 34441397, 2021). "It seems that CD44 may represent an important biomarker and a promising therapeutic target in canine gastric carcinomas." (PMID 34069167, 2021). "In gastric cancers, the expression of CD44 and CD90 correlated with distant metastasis and could therefore be used as a diagnostic biomarker and was suggested as a biomarker for treatment response." (PMID 32849491, 2020). "Regarding gastric cancer, miR-145 modulates CD44 by directly targeting its 3′UTR." (PMID 32366274, 2020). "Nishii 28 found that high expression of stem cell markers could isolate gastric cancer cell line with high potential for peritoneal metastasis, such as CD44, OCT4 and SOX2." (PMID 32788883, 2020). "The single nucleotide polymorphism (SNP) rs8193, locatedin the CD44 gene, has not been studied in gastric cancer patients of the Iranian population." (PMID 31376327, 2020). "In vitro experiments, Takaishi 26 added the selected CD44 positive gastric cancer cell into the serum-free medium containing EGF and bFGF, and they could form spherical clones after a few weeks." (PMID 32788883, 2020). "In gastric cancer patients, CD44+ circulating tumor cells correlated with a poor prognosis." (PMID 32849491, 2020). "For instance, CD44 showed increased resistance for chemotherapy- or radiation-induced cell death and was previously identified as a marker gene for gastric cancer stem cells." (PMID 33363566, 2020). "In gastric cancer, CD44 and CD133 were also reported to be relevant to chemoresistance." (PMID 31619711, 2019). "Additionally, suppressing SPARC expression in GCAFs facilitated the phenotypic alteration of gastric cancer cells towards CD44+/CD24− cancer stem cell (CSC)-like cells." (PMID 31139014, 2019). "Moreover, CD44 expression was significantly associated with the expression of EMT-related molecules E-cadherin, Vimentin, Snail-1, and ZEB-1 in gastric cancer patients." (PMID 30696080, 2019). "Notably, gastric cancer stem cells are characterized by the expression of CD44, which is a target gene of the Wnt signaling pathway." (PMID 30884828, 2019). "The splicing product of the CD44 gene CD44v8-10 was significantly upregulated in gastric cancer." (PMID 31744495, 2019). "In gastric cancer, CD44 is considered a CSC biomarker for chemoresistance and progression." (PMID 31139014, 2019). "In addition, Wnt-1 was related to CD44 expression, while inhibition of the Wnt/β-catenin pathway suppressed gastric cancer stem cells." (PMID 30884828, 2019). "This could be at least partially attributed to the highly malignant potential of the subpopulation of CD44+ gastric cancer cells, as demonstrated by patient-derived tumor xenograft models." (PMID 30056567, 2019). "Therefore, SALL4 likely promotes gastric cancer progression, at least in part, by directly activating CD44 expression." (PMID 29747682, 2018).
gastric cancer (continued). "Lastly, as a mucin-type O-glycosylation it may be carried by a wide range of secreted glycoproteins that are overexpressed in gastric cancer such as MUC1 or CD44." (PMID 30189652, 2018). "Strong correlation of OPN and CD44 expression was detected in 243 gastric cancer patients’ tissues." (PMID 29747682, 2018). "These cells form spheres in a high efficiency and lead to tumor formation when injected in to the gastric cavity and skin of the SCID (severe combined immunodeficiency) mice, indicating that CD44-positive gastric cancer cell subsets have potent in vivo tumor-initiating capacity." (PMID 29422082, 2018). "Moreover, bELE inhibits the viability of gastric cancer stem‐like cells (CD44+) in a dose‐dependent manner and attenuates angiogenesis." (PMID 28297578, 2017). "The cell surface marker CD44 is expressed in gastric cancer cells, and targeting of which may eliminate cancer cells resistant to radiation or chemotherapy." (PMID 29212456, 2017). "Similarly, using another gastric cancer stem cell marker, CD44, Notch1 and Hes1 were found to be highly expressed in gastric cancer stem-like cells (GCSCs)of MKN45 cells." (PMID 28881855, 2017). "Moreover, CD44 rs187116 genotype has been suggested for use as identifying and predicting the clinical outcome of gastric cancer patients." (PMID 29445738, 2017). "CD44 has been identified as a marker of gastric cancer stem cells." (PMID 28147337, 2017). "Our study indicate that expression of CD44 could be used as a marker for the prediction of gastric cancer development, especially in patients with precancerous gastric lesions, who were selected to surveillance follow-up for gastric cancer prevention." (PMID 29445738, 2017). "Cd44 is one of the most reliable marker for targeting gastric cancer, and elimination of CD44-positive cells using sulfasalazine plus cisplatin in patients with advanced gastric cancer has been attempted." (PMID 29212456, 2017). "Despite there being many studies of the expression of CD44 in gastric cancer worldwide, it is unknown which CSCs marker could be more effective to predict gastric cancer development." (PMID 29445738, 2017). "In particular, we identified CD44 as a downstream target of SALL4 in gastric cancer cells." (PMID 27819668, 2016). "CD44 is a well-recognized stem cell biomarker expressed in colon and gastric cancer." (PMID 27323782, 2016). "ChIP studies showed that the endogenous SALL4 protein could bind to the specific promoter region of CD44 in gastric cancer cells, suggesting that CD44 is a direct target of SALL4." (PMID 27819668, 2016). "Additionally, we investigated the effect of AQP3 on CD44 expression and stem-like properties of gastric cancer cells and elucidated the mechanism involved in this effect." (PMID 26918728, 2016). "However, the clinical impact and interaction between the Shh pathway and CD44 expression in gastric cancer patients are still uncertain." (PMID 26839535, 2016). "In this study, we further found that YM155, a specific survivin suppressant, induced apoptosis of gastric cancer cells, inhibited expansion of gastric CSCs and reduced expression of CSC molecules (CD44 and β-catanin) and suppressed gastric cancer xenograft growth." (PMID 26771139, 2016). "Despite their suggested importance, the mechanistic roles of FGFR2 and gastric cancer stem cell (GCSC) marker CD44 remain unclear." (PMID 27107424, 2016). "However, most studies exploring the role of CD44 protein in gastric cancer included patients that received either radical resection or palliative surgery, which introduced bias into the studies." (PMID 26839535, 2016). "High level of CD44 mRNA could improve the survival rate in the patients with intestinal-type gastric cancer (P = 0.035)." (PMID 27323782, 2016).
gastric cancer (continued). "YM155 treatment downregulated expression of CD44 in gastric cancer cells." (PMID 26771139, 2016). "To determine whether Ad-Bmi-1i has inhibitory or killing effect on gastric CSC-like cells, we detected the expression of CD133 and CD44 by Immunohistochemistry (IHC) in Ad-Bmi-1i treated gastric cancer xenografts (Ad-Bmi-1i) and in control group (Ad-Ctrli)." (PMID 27009837, 2016). "Additionally, binding of OPN-a to CD44 variants activates integrins through Src, thus promoting ECM-derived survival signals in gastric cancer." (PMID 27487131, 2016). "In order to identify whether CD44 mRNA could be used as a prognostic marker in colon and gastric cancer, bioinformatic analyses were used in this study." (PMID 27323782, 2016). "Moreover, overexpression of CD44 in SALL4 knockdown cells led to increased gastric cancer cell proliferation, migration and invasion in vitro as well as increased tumour growth in mouse models." (PMID 27819668, 2016). "Noteworthy, CD44 acts as stem cell surface marker in both nasopharyngeal carcinoma and gastric cancer, the inhibition of CD44 expression by grifolin may contribute to its inhibitory effect on tumor invasion." (PMID 27626695, 2016). "This may partially explain why CD44 and Shh signaling pathway signatures are useful biomarkers for aggressive tumour behaviour in gastric cancer." (PMID 26839535, 2016). "No previous studies have clarified the association between CD44 overexpression and tumour relapse or long-term survival only in gastric cancer patients who received radical resection." (PMID 26839535, 2016). "To demonstrate whether SALL4 knockdown affects the expression of both standard and variant isoforms of CD44, we examined the expression of CD44s and CD44v6, a CD44 variant that is closely related to gastric cancer, in SALL4 knockdown gastric cancer cells." (PMID 27819668, 2016). "CD44 is a cell surface adhesionmolecule, expressed on a variety of cells including gastric epithelial cells, that hasrecently been identified as a gastric cancer stem cell marker, whereby cells expressingCD44 have been shown to possess the properties of gastric cancer stem cells." (PMID 25658601, 2015). "In our study, ∼90% of the MKN45 and MKN47 gastric cancer cells highly co-expressed CD44 and CD47." (PMID 26077800, 2015). "CD44 had been reported to express strongly in the nucleus and cell membrane in gastric cancer." (PMID 26540347, 2015). "We therefore considered that higher expression of CD44 in gastric cancer cells may represent a higher percentage of CSCs, thus explaining why CD44(+) patients demonstrate poorer overall survival than CD44(−) patients." (PMID 25212506, 2014). "CD24 and CD44 expression were detected in the membrane of cancer cells in gastric cancer samples." (PMID 25212506, 2014). "Weak staining for both CD24 and CD44 was also observed in the nucleus of gastric cancer cells." (PMID 25212506, 2014). "The frequency of CD44 expression in gastric cancer varies widely from 31 to 72%." (PMID 25212506, 2014). "Gastric cancer stem cell will express a specific surface marker CD44." (PMID 25197668, 2014). "Cancer stem cells (CSCs) have recently been identified in human gastric cancer cell lines in several studies, and CD44(+)CD24(+) cells have been shown to define a highly tumorigenic, gastric cancer cell population with properties of self-regeneration and multi-lineage differentiation." (PMID 25212506, 2014). "Based on these previous studies, we hypothesized that CD24 and CD44 expression might be correlated with gastric cancer prognosis." (PMID 25212506, 2014). "Different frequencies of CD44+ cells in gastric carcinomas reported in various studies could be due to geographic variation and various CD44 antibodies were used to identify isomers." (PMID 25635255, 2014). "Other group reported that CD44 was a good marker of gastric cancer stem cell." (PMID 23593346, 2013).
gastric cancer (continued). "Accumulating evidences have shown that CD44 is abundantly expressed in cancer-initiating cells (CICs), and has thus been implicated as a CIC marker in several malignancies of haematopoietic and epithelial origin, including gastric cancer." (PMID 22606006, 2012). "Based on the implications of these previous studies, we hypothesized that CD44+/CD24- expression might be correlated with gastric cancer recurrence." (PMID 22839505, 2012). "In addition, advance in gastric cancer stem cell markers such as CD44, CD90, CD133, Musashi-1 reveal novel information on tumor cell behavior and disease progression implicated for therapeutics." (PMID 23217022, 2012). "Finally the surface marker of colorectal and gastric cancer stem cells CD44 revealed a distribution comparable with Msh-1." (PMID 22530031, 2012). "After adjusting for other risk factors, the association of CD44/CD24 expression with gastric cancer recurrence was still not significant." (PMID 22839505, 2012). "Therefore, we decided to investigate the expression of adhesion molecule CD44/CD24 in recurrent gastric cancer and its possible predictive relevance in future clinical practice." (PMID 22839505, 2012). "No significance was shown in the crude association of CD44/CD24 expression with gastric cancer recurrence." (PMID 22839505, 2012). "In conclusion, neither individual expression of CD24 and CD44 nor combined expression of CD44/CD24 was associated with recurrence of gastric carcinoma." (PMID 22839505, 2012). "In addition to MKN7 and NUGC3, most genes, CD44 and Keratin family genes are strongly expressed in gastric cancer cells of peritoneal dissemination." (PMID 12402156, 2002). "ALDH+ and CD44+ CSCs subpopulations are often expressed in gastric cancer (GC) and non-small cell lung cancer (NSCLC)." (PMID 38515460, 2024). "High CD44 expression has been observed in gastric cancer stem cells, and SPP1-expressing TAMs correlated with a worse clinical outcome in gastric cancer, suggesting the SPP1/CD44 axis may be associated with stemness properties and resistance to anticancer therapies." (PMID 38521868, 2024). "Therefore, CD44+EpCAM+ cells were selected as gastric cancer stem cells for subsequent experiments." (PMID 36765401, 2023). "The CD44 expression may be mutually beneficial for gastric cancer cell invasion and metastasis." (PMID 37328876, 2023). "Shh-Gli1 signaling was activated in CD44+ gastric cancer stem cells, which was responsible for drug resistance in advanced GC." (PMID 37596267, 2023). "However, same characteristics are represented by CD44+ CD24+ cells in gastric cancer." (PMID 37529165, 2023). "However, the prognostic value of CD44 and its correlation with immune infiltration in gastric cancer remain unclear." (PMID 36316684, 2022). "In a study by Campos and colleagues, two O-glycoproteins, CD44 and GalNAc-T5 with O-glycan STn were observed in both GC cells and sera of patients with GC, and indicated as potential biomarkers in gastric cancer." (PMID 33198323, 2020). "Furthermore, HH/SMO inhibition could be helpful to reverse the chemoresistance of CD44+ spheroid gastric cancer cells to 5-fluorouracil and cisplatin." (PMID 32962123, 2020). "To confirm whether EGFR inhibition-mediated CD44v downregulation could cause the CD44v9-expressing cell-selective growth inhibition, we examined the effect of CD44 knockdown on the proliferation of CD44v9-positive and CD44v9-negative cells sorted from the gastric cancer PDCs." (PMID 31607750, 2019). "It was found that miR-328 could target CD44, and they showed a negative regulatory relationship between them, which indicated that detecting the expression level of miR-328 can be used as a means to predict the prognosis of gastric cancer patients." (PMID 31737678, 2019). "To identify tumor‐suppressive microRNAs repressed by DNA methylation in gastric cancer (GC), we analyzed the genome‐wide DNA methylation and microRNA expression profiles of EpCAM+/CD44+ GC cells." (PMID 29862663, 2018).